CSF1 (colony stimulating factor 1)
Diseases named in the same sentence as CSF1 in open-access papers (continued):
Sharing a sentence is not in itself a finding about the gene and the disease.
breast cancer (continued). "An increasing number of research articles have shown that SPP1 and CSF1 exhibit the same expression trend in multiple cancer types, including liver cancer, breast cancer, thyroid cancer, and lung cancer." (PMID 37097499, 2023). "Here, we assessed the impact of tumor-derived CSF1 by developing CSF1 CRISPR-Cas9 knockouts in the 4T1 mammary carcinoma and MC38 murine colon carcinoma cell lines, where mice harboring these tumors achieved tumor control when compared to the parental tumors." (PMID 37505292, 2023). "Accordingly, depletion of TAMs with anti-CSF1/CSF1R (CSF1 receptor) antibodies enhanced chemosensitivity to a combinatorial chemotherapeutic approach in human breast cancer xenografts and a genetic mammary tumor model." (PMID 35664746, 2022). "In co-cultures of breast cancer cells and monocytes, breast cancer cells secrete CSF1 and induce monocytes to express and release CXCL7, which in turn acts on cancer cells to promote FAK activation, MMP13 expression, migration, and invasion." (PMID 36407100, 2022). "In this study, we identified a novel enhancer that drives the expression of the oncogene CSF1 in triple-negative breast cancer patients, the most aggressive subtype of breast cancer." (PMID 35406623, 2022). "Transgenic mice overexpressing CSF-1 in their mammary epithelium presented an increased breast cancer metastatic potential, while overexpression of CSF-1/CSF-1R in human ovarian and breast carcinoma correlates with poor survival outcomes." (PMID 35804859, 2022). "The up-regulation of m1A demethylase ALKBH3 was shown to be involved in decay of macrophage-colony stimulating factor-1 (CSF-1) mRNA, which resulted in promoting breast cancer cell invasiveness." (PMID 35721510, 2022). "The cytokine colony-stimulating factor-1 (CSF1) stimulates macrophage recruitment and survival, and its expression is prognostic for mortality in breast cancer." (PMID 35202089, 2022). "IL34, CSF1 and their receptors co-expressed within the immune cell infiltrated area and regulated the different downstream signalling pathways in breast cancer." (PMID 35967449, 2022). "Mir-149 directly targets and inhibits CSF1 mRNA in breast cancer cells, limiting macrophage recruitment to the primary tumor." (PMID 35202089, 2022). "In this study, we leveraged eRNA expression to identify a novel enhancer of CSF1 that was active specifically in the TNBC subtype of breast cancer." (PMID 35406623, 2022). "Co-implantation of CSF-1/IL-4-generated M2 macrophages greatly enhanced tumor lymphatic formation and metastasis in lung and breast carcinoma mouse models, while depletion of M2-TAMs significantly inhibited both processes." (PMID 35442077, 2022). "Macrophages expressing EGF promote migration and invasiveness of breast carcinoma cells as well as CSF-1 expression by the latter, and cancer cell-derived CSF-1 is able to induce EGF production in macrophages." (PMID 35326399, 2022). "In a mammary cancer mouse model, CSF-1 promotes the growth of breast cancer cells and metastatic potential through recruiting TAMs to TME." (PMID 34359674, 2021). "Our findings shed a new light on our understanding of how CSF1 modulates TME to promote breast cancer progression through CXCL7-mediated signaling pathway." (PMID 34789744, 2021). "What’s more, paclitaxel treatment of breast cancer cells enhances the secretion of CSF-1, recruiting TAMs so as to limit the therapeutic effect." (PMID 34717710, 2021). "More than 70% of human breast cancers express colony stimulating factor 1 (CSF-1), which is a key regulator of mononuclear phagocytic lineage; and expression of CSF-1 is correlated with poor prognosis." (PMID 34336660, 2021). "Other preclinical studies have shown a significant correlation between CSF-1 and breast cancer metastasis using the MMTV-PyMT model." (PMID 33968034, 2021).
breast cancer (continued). "One such example involves EGF/CSF1 paracrine loop between breast cancer cells and macrophages, where tumor cells secrete CSF1 to recruit macrophages, and in turn, macrophages release EGF to stimulate tumor cell invasion towards blood vessels." (PMID 33540535, 2021). "In contrast, in breast cancer cells, TGFβ signaling increases the kindlin-2–mediated but integrin-independent expression of colony-stimulating factor 1 (CSF-1) that recruits macrophages, driving tumor progression." (PMID 34131655, 2021). "In summary, our data indicate that breast cancer cells secrete CSF1 to induce monocytic expression and secretion of CXCL7 in the TME." (PMID 34789744, 2021). "Overall, our study identifies a novel crosstalk mechanism between breast cancer cells and monocytes to facilitate breast cancer progression and metastasis through CSF1/CXCL7 axis." (PMID 34789744, 2021). "Activation of this pathway or a higher expression of either CSF-1 or CSF-1R results in poor prognosis of breast cancer in postmenopausal women." (PMID 34207035, 2021). "Ex vivo incubation of isolated tumor cells with EGCG inhibited the colony-stimulating factor 1 (CSF1), which is involved in breast cancer progression through inducing monocyte differentiation and homing." (PMID 34444715, 2021). "Here we identified a novel crosstalk between monocytes and breast cancer cells, in which monocytes secrete CXCL7 in response to CSF1 released from invasive breast cancer cells, and in turn CXCL7 acts on cancer cells." (PMID 34789744, 2021). "Blocking CSF1 in breast cancer-bearing mice reversed these effects and increased mouse survival rate." (PMID 33747948, 2021). "In breast cancer, colony-stimulating factor 1 (CSF-1) was identified to promote metastatic potential leading to progression of the tumor to malignancy, and overexpression of CSF-1 is associated with poor prognosis." (PMID 34539781, 2021). "Here our data reveal that CSF1, secreted by breast cancer cells stimulated CXCL7 expression from monocytes to promote monocyte recruitments, and to enhance cancer cell migration and invasion." (PMID 34789744, 2021). "Further investigations indicated that upon co-culturing, breast cancer cells secreted CSF1 to induce expression and release of CXCL7 from monocytes, which in turn acted on cancer cells to promote FAK activation, MMP13 expression, migration, and invasion." (PMID 34789744, 2021). "Enhanced CD8+ T cell infiltration and improved response to chemotherapy was also observed in the spontaneous mammary carcinoma MMTV-PyMT mouse model following anti-CSF-1 antibody mediated macrophage depletion." (PMID 33924237, 2021). "Previous studies showed that deleting Colony Stimulating Factor-1 (CSF-1/M-CSF) in the mouse mammary tumor virus–polyoma virus middle T antigen breast cancer mouse model (MMTV-PyMT) delayed metastatic tumor progression without altering mammary tumor growth." (PMID 34298673, 2021). "In mammary carcinoma-bearing transgenic PyMT mice, CSF-1 was upregulated after exposure to paclitaxel, which was believed to contribute to the recruitment of macrophages to the tumor; combined αCSF-1 and paclitaxel significantly delayed tumor growth." (PMID 33537102, 2021). "According to a related study, the gene inhibition of CSF1 in breast cancer cells affects tumor formation in immunodeficient mice." (PMID 32408477, 2020). "For example, in breast cancer, CSF-1 secreted from cancer cells and vascular endothelial growth factor (VEGF) secreted from TAM mutually stimulate the secretion of these factors, resulting in the acceleration of tumor infiltration and intravascular invasion." (PMID 31963413, 2020).
breast cancer (continued). "In animal models, perivascular macrophages contribute to breast cancer intravasation, which was assisted through positive feedback interactions between EGF from TAM and CSF1 from breast cancer cells." (PMID 32726950, 2020). "Another preclinical study demonstrated that blocking CSF-1 limits macrophage infiltration and improves response of mammary carcinomas to chemotherapy." (PMID 33276524, 2020). "Several studies showed that TAMs depletion by inhibiting CSF1 displays substantial attenuation in angiogenic potential and tumor burden in breast cancer." (PMID 31629410, 2019). "Another study revealed that pharmacological blockade of CSF-1/CSF-1R targeted specifically breast cancer CD11b+ Ly6Gneg Ly6Clow F4/80+ TAMs and induced increase in CD8+ lymphocyte infiltration." (PMID 31331034, 2019). "In MCF-7 mammary carcinoma cell xenografts CSF-1 block has been shown to reduce host macrophage infiltration and suppress tumor growth." (PMID 31406165, 2019). "It is also reported that depletion of MAMs by CSF1 or its receptor knockout reduces metastatic tumor burden in mice that are intravenously injected with mammary tumor cells." (PMID 30483271, 2018). "In vitro experiments showed that tyrosine phosphorylation of CSF-1R, ERK, and FAK and cell migration are differentially regulated by IL-34 and CSF-1 in breast cancer cell lines." (PMID 29796177, 2018). "CSF-1 was expressed at varying transcriptional and protein levels across all types of breast cancers." (PMID 29930294, 2018). "Inflammatory markers such as C-reactive protein in esophageal squamous cancer, Colony-stimulating factor-1 in mammary tumor, and inhibitors of metalloproteinases in NSCLC, all have been suggested as alternative markers for tumor progression." (PMID 30348119, 2018). "In a breast cancer model, primary macrophages increased transendothelial migration of primary breast cancer xenografts mediated by colony-stimulating factor-1 (CSF-1) and increased expression of CSF-1 receptor on tumor cells." (PMID 29596520, 2018). "Collectively, these results indicated that IL-34 and CSF-1 differentially activated signaling pathways in three breast cancer cell lines representing luminal, HER-2 and basal intrinsic subtypes." (PMID 29796177, 2018). "When analyzed by Western blotting, we found no obvious difference in the strength of CSF-1R, ERK, and FAK activation between IL-34- and CSF-1-stimulated MCF-7 breast cancer cells." (PMID 29796177, 2018). "For example, depletion of MAMs by CSF1 knockout reduces the number of cancer cells outside the blood vessels in the lung of mice that are intravenously injected with MET-1 mouse mammary tumor cells." (PMID 30483271, 2018). "Analysis of CSF-1 and CSF-1R expression in molecular breast cancer subtypes revealed generally lower levels for both when compared to normal tissue." (PMID 29796177, 2018). "By comparing stromal, immune and ESTIMATE scores in intrinsic breast cancer subtypes, we identified strong relationships of CSF-1 and CSF-1R to all scores." (PMID 29796177, 2018). "In the PyMT breast cancer mouse model, CSF-1 produced by tumor cells and EGF secreted by TAMs results in the migration of both macrophages and cancer cells along collagen fibers and intravasation into the blood vessels." (PMID 30356656, 2018). "We therefore focused on the CSF-1/CSF-1R axis and next studied the expression of CSF-1 at the transcriptional and protein levels in a panel of breast cancer cells." (PMID 29930294, 2018). "CSF1 is required for survival of immunosuppressive TAMs that promote angiogenesis and tumor metastasis and studies in mouse models of breast cancer have shown TAM recruitment into the tumor due to CSF-1/CSF-1R signaling." (PMID 29862083, 2018). "Neutralization of TAM-derived IL-10 enhanced T cell responses to a similar extent as TAM depletion using anti-CSF-1 antibodies in a spontaneous breast cancer mouse model." (PMID 30355585, 2018).
breast cancer (continued). "Together, our results define an NCOA1/ ___?___ /CSF1 regulatory axis that promotes breast cancer metastasis, offering a novel therapeutic target for impeding this process." (PMID 29305341, 2018). "Previous work has shown paracrine loop signaling between tumor cells and macrophages, where epidermal growth factor (EGF) from macrophages induced by colony stimulating factor 1 (CSF-1) from tumor cells contributes to breast cancer cell motility and invasion." (PMID 29636067, 2018). "Characterization of macrophage phenotypes in breast cancer subtypes using CIBERSORT_LM22 values and the TCIA database showed, as expected, that CSF-1/CSF-1R expression was positively associated with macrophages in all subtypes in the analyzed dataset." (PMID 29796177, 2018). "Our previous breast cancer studies found that CSF-1/CSF-1R signaling promotes tumor growth and it has been demonstrated that CSF-1R blockade using antibodies reduced the number of resident tumor-associated macrophages (TAMs) in tumors." (PMID 29796177, 2018). "In vitro experiments in luminal and basal type breast cancer cells revealed that IL-34 and CSF-1 differentially regulate cancer cell migration dependent on the molecular subtype." (PMID 29796177, 2018). "Previous studies have shown that there is paracrine loop signaling between breast cancer cells and macrophages involving colony stimulating factor 1 (CSF-1) produced by tumor cells and epidermal growth factor (EGF) production by macrophages." (PMID 29636067, 2018). "For instance, the attraction of TAMs in a MCF-7 breast cancer xenograft model, via CSF-1 signaling, reduces the efficacy of a combination treatment with cyclophosphamide, methotrexate and 5-fluorouracil (CMF)." (PMID 30356656, 2018). "For example, in a mouse model of breast cancer, expression of CSF-1 was highest at the invasive edge of the malignancy, which was consequently enriched with M2 macrophages." (PMID 28670313, 2017). "Accordingly, high TAM densities correlate strongly with metastatic breast cancer, and high CSF-1 levels coincide with dense TAM foci at invading fronts of breast cancers." (PMID 28629162, 2017). "Blockade of CSF-1 and CSF-1R in combination with chemotherapy improved survival and reduced the metastatic frequency in a breast cancer model and this response correlated with an increase in cytotoxic CD8+ T cells within the tumours." (PMID 28210073, 2017). "Elevated serum levels of CSF-1 have been found in patients with breast cancer, and even higher in patients with invasive cancer and concomitant lymph node metastasis." (PMID 28779164, 2017). "Hypoxia induces CCL5 expression in mesenchymal stem cells which binds also to hypoxia induced CCR5 in breast cancer cells leading to higher tumoral CSF-1 expression which drives the recruitment of TAMs and MDSCs." (PMID 28197019, 2017). "Quantitative PCR revealed high levels of CSF-1 message in these cells compared with more differentiated luminal breast cancer cells." (PMID 31453214, 2016). "Previous studies revealed that macrophages stimulate breast cancer cell migration and invasion through a paracrine loop involving colony-stimulating factor-1 (CSF-1), produced by cancer cells, and EGF produced by macrophages." (PMID 26043921, 2015). "These analyses revealed CSF-1 to be predominantly expressed in lung brain metastases and to a lesser extend in brain metastases arising from breast cancer." (PMID 26098772, 2015). "During the M1-to-M2 transition of macrophages the molecular changes occurring can have profound effect on breast cancer cell behaviour; notably, the levels of the cytokines CSF-1 and CCL2 are elevated during this transition." (PMID 26174804, 2015). "The significant impact of CSF-1 is well demonstrated in the spontaneous metastasizing MMTV-PymT-transgenic mouse model of breast cancer." (PMID 26098772, 2015). "In this study we sought to analyze the effects of an anti-CSF-1 antibody (clone 5A1) on MC-induced invasiveness of breast cancer cells." (PMID 26098772, 2015).
breast cancer (continued). "In mammary tumors, TAMs were reported to promote cell invasion and the production of colony-stimulating factor-1 (CSF-1) by releasing epidermal growth factor via a paracrine loop." (PMID 25884955, 2015). "During breast cancer progression the colony stimulating factor 1 (CSF-1) can reprogram MCs into tumor-promoting macrophages in the primary tumor." (PMID 26098772, 2015). "Overall, our results demonstrate the extent to which canine mammary carcinoma cells influence the macrophage phenotype and the relevance of a feedback loop between these cells, involving CSF-1 and CCL2 as important mediators." (PMID 26174804, 2015). "In a murine mammary carcinoma model, CSF-1 produced by tumor cells stimulated tumor macrophages to produce epidermal growth factor (EGF) which stimulated cancer cell chemotaxis and microvessel intravasation." (PMID 26317041, 2015). "The use of anti-sense and siRNA toward CSF1 or its receptor further demonstrated its role in growth of breast cancer xenografts." (PMID 25313137, 2014). "Direct evidence of the role of TAMs in tumor progression is observed in breast cancer mouse models in which colony-stimulating factor-1 (CSF-1)-dependent TAM recruitment is required for tumor initiation through the stimulation of tumor angiogenesis." (PMID 26237389, 2014). "For instance, a reciprocal interaction exists between macrophages and breast cancer cells whereby the tumor cells produce CSF1 and express the receptor for EGF while macrophages produce EGF and express the receptor for CSF1." (PMID 25313137, 2014). "Pollard (2004) suggests that there is a correlation between the expression of CSF-1 and poor prognosis in breast cancers which is due to the availability of CSF-1 to recruit and modulate the behaviour of TAMs." (PMID 24808960, 2014). "Overexpression of colony stimulating factor (CSF-1) in breast cancer leads to development of bone metastasis." (PMID 25147739, 2014). "Sapi (2004) reported that 58% of all breast cancers and 85% of invasive breast carcinomas expressed high levels of CSF-1, and this expression was clearly localised in the neoplastic epithelial cells of the tumours as well as in the stromal macrophages." (PMID 24808960, 2014). "Previous reports implicate Colony stimulating factor-1 (CSF-1) secreted by breast cancer cells as potent chemoattractant for macrophages." (PMID 25051364, 2014). "The breast cancer metastasis model addresses the effect of the CD115 mAb on bone-resorbing osteoclasts induced by tumor cells secreting CSF-1." (PMID 24019914, 2013). "Based on our previous findings, the DTF signature robustly defined a stromal pattern for 25 to 35% of invasive breast cancers, while the TGCT/CSF1 signature was found in 17 to 28% of breast cancers." (PMID 24342436, 2013). "These previous findings suggest that breast cancer cells release mediators, such as CSF-1 and IL-1, to activate tumor-infiltrating macrophages to produce MCP-1." (PMID 23527025, 2013). "Condeelis group indicate that both autocrine and paracrine CSF-1 loops significantly contribute to dissemination of cancer cells and progression in human breast cancer." (PMID 23561040, 2013). "To assess more accurately the effect of CSF-1 on canine mammary cancer cells invasion, we conducted the invasion assay of highly invasive cell lines in Boyden chambers." (PMID 23561040, 2013). "The FOTS+/TGCT/CSF1- breast cancer showed the worst outcome in overall survival, disease specific survival and disease free survival." (PMID 24342436, 2013). "In a chemoresistant MCF-7 breast cancer model, combined chemotherapy (cyclophosphamide, methotrexate, and 5-fluorouracil), when used in conjunction with anti-CSF-1 antibodies, displayed markedly enhanced antitumor efficacy." (PMID 24314323, 2013).